IL22 (interleukin 22)
Diseases named in the same sentence as IL22 in open-access papers (continued):
Sharing a sentence is not in itself a finding about the gene and the disease.
ulcerative colitis (54 papers, 2010 to 2026). An inflammatory bowel disease involving the mucosal surface of the large intestine and rectum. "IL-22 modulates neutrophil recruitment to the colon by controlling the expression of neutrophil-active CXC-family chemokines in ulcerative colitis; by this mechanism, the augmented expression of IL-22 is associated with treatment resistance to an anti-IL-12/23 p40 subunit monoclonal antibody." (PMID 36769019, 2023). "Here, the authors show that the transcriptional program regulated by IL-22, an IL-23 responsive cytokine, is enriched in patients with ulcerative colitis unresponsive to ustekinumab and associated with higher colon neutrophil recruitment and activation of upstream IL-22 regulators." (PMID 36192482, 2022). "In a DSS-induced mouse organoid inflammation model, Hymenolepis nana antigens promote intestinal stem cell proliferation and differentiation through the AhR/IL-22 signaling pathway, thereby alleviating ulcerative colitis." (PMID 41019044, 2025). "In this study, we explore the role of IL-22 and IL-22-induced hemopexin in the context of experimental ulcerative colitis using the dextran sodium sulphate (DSS) mouse model of acute colitis." (PMID 40791589, 2025). "In ulcerative colitis, interleukin-22 (IL-22) plays a crucial role by promoting mucosal healing and regulating the inflammatory response." (PMID 38798981, 2024). "• This protocol is developed to assess the delivery of IL-22 mRNA to ulcerative colitis sites using lipid nanoparticles." (PMID 38798981, 2024). "In a prior study, we engineered LNPs loaded with IL-22 mRNA for treating ulcerative colitis, evaluating the biodistribution of DiR-labeled IL-22/LNP." (PMID 38798981, 2024). "Anthocyanin-rich bilberry extract was found to lower the levels of proinflammatory cytokines IFN-γ and TNF while increasing the levels of Th17 cell-specific cytokine IL-22 and immunoregulatory cytokine IL-10 in ulcerative colitis patients." (PMID 35204188, 2022). "Here, we map the transcriptional landscape regulated by IL-22 in human colonic epithelial organoids and evaluate the biological, functional and clinical significance of the IL-22 mediated pathways in ulcerative colitis (UC)." (PMID 36192482, 2022). "Bioactive compound such as interleukin-22 (IL-22) treatment is regarded as a sufficient treatment for ulcerative colitis (UC)." (PMID 36092152, 2022). "Mirt2 has been proven to be a negative regulator of multiple inflammatory diseases such as ulcerative colitis, in which Mirt2 is downregulated and regulates the expression of IL‐22 to suppress cell apoptosis." (PMID 33943017, 2021). "A significantly reduced expression of IL-22 has been noticed in intestinal mucosa of ulcerative colitis patients due to increased concentration of TGF-β as compared to healthy colon tissues." (PMID 33042126, 2020). "IL-22 is considered a promising target for tissue-protective therapy, especially in acute disease of epithelial tissues, such as ulcerative colitis or hepatitis." (PMID 32517220, 2020). "IL-20, IL-22, and IL-24 have been found to be higher in the colons of patients with ulcerative colitis, where mucosal epithelial damage is very common." (PMID 31311100, 2019). "The interleukin (IL)-20 subfamily of cytokines consists of IL-19, IL-20, IL-22, IL-24, and IL-26, and the expression of IL-20, IL-22, and IL-24 is reported to be higher in the colon of patients with ulcerative colitis." (PMID 31311100, 2019). "It has been found that the expression levels of IL-20, IL-22, and IL-24 are higher in the colon of patients with ulcerative colitis but that their roles in colonic epithelial renewal are not clearly understood." (PMID 31311100, 2019). "In addition, IL-22 signaling may provide a clue to solve a long-standing epidemiologic mystery in IBD regarding a negative association of cigarette smoking with the development of ulcerative colitis (UC)." (PMID 29075900, 2018).
ulcerative colitis (continued). "IL-22-deficient mice have increased susceptibility to hepatitis and similarly overexpression of the IL-22 gene in a mouse model of ulcerative colitis rescues the disease phenotype." (PMID 29163483, 2017). "In contrast, ILC3 from patients with mild-moderate ulcerative colitis were reported to have increased IL-22 production." (PMID 27055194, 2016). "A report of self-infection with the nematode parasite Trichuris trichiura to treat ulcerative colitis documented increased numbers of CD4+IL22+ cells." (PMID 27055194, 2016). "Fewer IL-22+ cells have been described in inflamed tissue from patients with ulcerative colitis compared to healthy individuals." (PMID 27055194, 2016). "It is therefore of interest that infection with the helminth Trichuris trichiura has been reported to therapeutically alleviate ulcerative colitis by a mechanism that is dependent on expansion of IL‐22–positive cells." (PMID 24497523, 2014). "In contrast, an IL-22 gene-delivery system ameliorates intestinal inflammation in a mouse model of ulcerative colitis." (PMID 24040208, 2013). "We previously found that IL-22 producing CD4+ cells were associated with helminth infection and disease remission in a patient with ulcerative colitis." (PMID 22829946, 2012). "Therapeutic interventions targeting the AhR/IL-22 axis may offer novel avenues for the management of ulcerative colitis, potentially enhancing autophagic processes and improving intestinal health outcomes." (PMID 41019044, 2025). "Since IL-1β, IL-6 and TL1A are all capable of inducing IL-22 production, it is possible that pathway redundancy and IL-23-independent induction of IL-22 might contribute to ustekinumab resistance in ulcerative colitis." (PMID 36192482, 2022). "Therefore, Mirt2 is downregulated in ulcerative colitis and regulates IL-22 expression in colonic epithelial cells." (PMID 31687015, 2019). "Here, we found that mucosal expression of genes involved in the purine metabolic pathway is altered in patients with active ulcerative colitis (UC), which is associated with elevated gene expression signatures of the group 3 innate lymphoid cell (ILC3)–interleukin (IL)‐22 pathway." (PMID 29758102, 2018). "Indeed, indigo naturalis, which can activate IL-22 pathway through Ahr, has been shown in a clinical trial to exhibit a strong therapeutic effect on ulcerative colitis." (PMID 29075900, 2018). "IL-22 expression was found to be increased in patients with ulcerative colitis (UC)." (PMID 25297677, 2014). "Moreover, our findings demonstrated that IL-22 expression was significantly higher in ulcerative colitis (UC) tissues versus normal colon tissues." (PMID 23379788, 2013). "Besides antigen specific Th17 cells, IL-22 production is characteristic of ILC3s, a cellular type most abundant in the intestine and one that is significantly and selectively increased in CD compared with healthy donors or ulcerative colitis (UC) patients." (PMID 30405600, 2018). "CSF3R expression was positively correlated with IL22 and IL23 expression in patients with ulcerative colitis, and patients with higher CSF3R expression were also found to have enriched epithelial repair and regeneration gene profiles." (PMID 40906170, 2025). "Simultaneously, it enhances the integrity of the intestinal epithelial barrier via the AhR/IL-22 pathway in ILC3, thereby ameliorating ulcerative colitis." (PMID 38962743, 2024). "Olsalazine significantly increased the contents of IL-2, IL-10, IL-22, TGF and EGF in ulcerative colitis rats, and significantly decreased the scores of DAI, CMDI, HS and the contents in IL-7, IL-17, TNF-α, IL-1β and IFN-γ when compared with the model group." (PMID 37610966, 2023). "Indirect stimulation of IL-22RA1 through IL-22 gene transduction or IL-22–producing immune cell transfer has shown beneficial impacts in small intestinal epithelial regeneration and in dextran sodium sulfate (DSS)–induced ulcerative colitis." (PMID 37695525, 2023).
ulcerative colitis (continued). "It was suggested that olsalazine has a therapeutic effect on ulcerative colitis induced by DSS in mice, and the mechanism may be related to the increase of IL-2, IL-10, IL-22, TGF, and EGF and the decrease of the expression of IL-7, IL-17, TNF-α, IL-1β, and IFN-γ." (PMID 37610966, 2023). "Supplementation of IL-22 may be an effective treatment, and local IL-22 gene delivery improves intestinal inflammation by enhanced signal transducer and activator of transcription 3 (STAT3) activation within colonic epithelial cells in the murine model of ulcerative colitis." (PMID 34975838, 2021).
COVID-19 (53 papers, 2020 to 2026). A disease caused by infection with severe acute respiratory syndrome coronavirus 2. "IL12p70, a target of ustekinumab, and IL22, which is important for maintenance of intestinal homeostasis, were found in signatures associated with worsening COVID-19 severity." (PMID 38168138, 2024). "Higher concentrations of IL-22 and IL-33 were associated with an increased risk of COVID-19 (IL-22: OR = 17.80 [95% CI: 6.48–48.90], p = 0.001); IL-33: OR = 19.0 [95% CI: 7.4–48.6], p = 0.001)." (PMID 36875710, 2023). "Multinomial logistic regression analysis was performed to assess the significance of IL-22 and IL-33 as factors associated with COVID-19 risk." (PMID 36875710, 2023). "IFN-lambda (p = 0.03) and IL-22 (p = 0.002) were significantly associated with COVID-19 severity and remained significant in linear regression analysis while controlling for other variables." (PMID 37896822, 2023). "Among them, AAbs for interleukin 22 were significantly associated with COVID-19 severity (p = 0.002)." (PMID 37896822, 2023). "This study analyzed serum concentrations of interleukin (IL)-22 and IL-33 (pro-inflammatory and anti-inflammatory cytokines) in 90 patients with mild/moderate coronavirus disease 2019 (COVID-19) and 90 healthy controls." (PMID 36875710, 2023). "It has been well documented that ESR and GLR are inflammatory markers associated with the pathogenesis of COVID-19, and IL-22 and IL-33 may represent additional inflammatory markers associated with the development of mild/moderate SARS-CoV-2 infection." (PMID 36875710, 2023). "IL-22 is a member of the IL-10 family of cytokines implicated in antiviral immune responses, and more especially during pulmonary infection; like IL-10, it has the double function of suppressing or encouraging inflammation in various disease models, but its role in COVID-19 remains elusive." (PMID 35911747, 2022). "Consistently, increased levels of T-cell-related cytokines (IL-2, MIP-1α, MIP-3α, IL-10, Eotaxin, IL-8, IL-17A–D, and IL-22) have been found in plasma of individuals with DS; among them IL-10 and IL-8 are upregulated in severe COVID-19." (PMID 41490093, 2026). "Th22 cells play a re-epithelializing role through IL-22 production and both IL-13 and IL-22 are protective factors during acute and persistent COVID-19, promoting tissue protection and regeneration." (PMID 41181095, 2025). "The MCP-1, IL-18, and IFN- γ levels were higher in COVID-19 patients than in vaccinated HCWs, while IL-22 levels increased in the vaccinated HCWs group." (PMID 39258622, 2024). "In this study, the vaccination promoted an increased IL-22 production compared to that observed in COVID-19 patients." (PMID 39258622, 2024). "Taking into considerations our results, we believe that the protective effect of BNT162b2 mRNA COVID-19 vaccine via IL-22 induction is worth further investigation." (PMID 39845961, 2024). "In a separate investigation, elevated serum levels of IL-22 and IL-33 were observed in individuals with mild/moderate COVID-19." (PMID 38216935, 2024). "Median IL-22 and IL-33 concentrations were significantly elevated in COVID-19 patients compared with HC (IL-22: 18.6 [IQR: 18.0–19.3] vs. 13.9 [IQR: 12.1–14.9] pg/mL, p < 0.001); IL-33: 37.8 [IQR: 35.3–43.0] vs. 24.1 [IQR: 23.0–26.2] pg/mL, p < 0.001)." (PMID 36875710, 2023). "During the acute phase of COVID-19, the immune response leads to a dramatic increase in several cytokines, including IL-22, which is mainly produced by Th22 cells." (PMID 36839448, 2023). "The current study revealed that up-regulated concentrations of IL-22 were an excellent predictor of COVID-19 (AUC = 0.95)." (PMID 36875710, 2023). "On the other hand, in diseases such as Helicobacter pylori infection, hepatitis B and COVID-19, IL-22 induces disease progression by promoting local recruitment of inflammatory cells and secretion of proinflammatory cytokines." (PMID 36839448, 2023).
COVID-19 (continued). "IL-22 in COVID-19 is described to reduce the pneumonia severity via immune regulation and tissue protection." (PMID 37896822, 2023). "IL-22 and IL-33 showed up-regulated concentrations in the serum of patients with mild/moderate COVID-19." (PMID 36875710, 2023). "In this study, serum IL-22 and IL-33 concentrations were analyzed in patients with mild/moderate COVID-19 and compared with age-, sex- and BMI-matched HC." (PMID 36875710, 2023). "Consistent with our observation, IL-22 showed up-regulated serum levels in COVID-19 patients < 16 years of age." (PMID 36875710, 2023). "As indicated by the area under the curve (AUC), IL-22 and IL-33 were excellent predictors of COVID-19 (AUC = 0.95 and 0.892, respectively)." (PMID 36875710, 2023). "It is important to emphasise the importance of Th-17-type cytokine storm in the pathogenesis of COVID-19, IL-17 is produced by Th17 cells which are increased leading to increased production of IL-17 and IL-22 cytokines." (PMID 36016267, 2022). "Meanwhile, the patient with myopericarditis after COVID-19 vaccination showed a slightly increased level of Th17-type cytokines including IL-17A, IL-17F, and IL-22 compared to healthy controls, but they were lower than those of recently vaccinated controls." (PMID 35251049, 2022). "The expression of ACE2, AHR, and CARD9 was decreased in the ileum of the COVID-19 patients, and the expression of IL22, a cytokine regulated by aryl hydrocarbon receptor (AhR), was also decreased in the ileum of the COVID-19 patients." (PMID 36035409, 2022). "We found that fatal COVID-19 was associated with higher levels of IL6, IL10, IL22, CXCL10, CCL2, and CCL20 and lower levels of miR-495-3p, miR-451a, and miR-29b-3p." (PMID 34957382, 2022). "The expression of genes involved in tryptophan metabolism, including ACE2, AHR, CARD9, and IL22, was downregulated in the ileum of critical COVID-19 patients who required a colonoscopy." (PMID 36035409, 2022). "We summarize the latest progress in our understanding of IL-22 in lung health and disease and further discuss maneuvering this cytokine as potential immunotherapeutic strategy for the effective manage of COVID-19." (PMID 35967401, 2022). "The mucosal gene expression analysis showed both AHR and the downstream IL-22 gene were decreased in critical COVID-19 group." (PMID 36035409, 2022). "In addition, higher levels of proinflammatory Th9 and Th17 cell subsets were observed in comparison with acute forms of COVID-19, with a reduced capacity to express anti-inflammatory cytokines related to endothelial regeneration such as IL-22." (PMID 39257580, 2024). "Except for IL-8 decreased in the second trimester after infected with SARS-CoV-2, IL-2, TNF-α, TNF-β, IFN-γ, IL-4, IL-5, IL-6, IL-10, IL-17A, IL-17F, IL-22, IL-1β and IL-12p70 didn't change in the three trimesters between healthy pregnancies and pregnant women with COVID-19." (PMID 39113896, 2024). "The higher IL-22 expression in immunised individuals compared to those with COVID-19 suggests that IL-22 may be beneficial in protecting against severe disease." (PMID 39258622, 2024). "Higher levels of IL-22 expression in immunised individuals compared to those with moderate to severe COVID-19 suggests that this molecule may have a protective role in reducing disease severity in vaccinated individuals." (PMID 39258622, 2024). "Considering that COVID-19 exhibits characteristics and symptoms as other severe respiratory virus infections it is plausible to suggest that IL-22 might have a role, in reducing the severity of this respiratory disorder." (PMID 38216935, 2024). "Multinomial logistic regression analysis demonstrated that individuals with high production (> control median) of IL-22 (odds ratio = 17.80 [95% CI: 6.48–48.90]; p = 0.001) and IL-33 (odds ratio = 19.0 [95% CI: 7.4–48.6]; p = 0.001) were more likely to develop COVID-19." (PMID 36875710, 2023).